APOE (apolipoprotein E)
Diseases named in the same sentence as APOE in open-access papers (continued):
Sharing a sentence is not in itself a finding about the gene and the disease.
respiratory diseases (10 papers, 2014 to 2026). "Several investigations have shown that ApoE plays a significant role in pulmonary homeostasis and the pathogenesis of multiple respiratory diseases through its ability to attenuate inflammation, oxidative stress, and tissue remodeling responses." (PMID 37887075, 2023). "Correlations were evident for respiratory diseases in which APOE ε4 showed a protective tendency (OR = 0.515; p = 0.088), and BIN1 had a significative protective profile (OR = 0.556; p = 0.026)." (PMID 39081475, 2022). "Nearly all baseline characteristics were associated with antidepressant use, except for body mass index, respiratory diseases, ischemic pathologies, and ApoE ε4." (PMID 28424070, 2017). "Interestingly, apolipoprotein E (ApoE), which has previously been attributed a protective role in respiratory disease, was strongly and significantly downregulated across all MC clusters in AERD patients." (PMID 35418991, 2022).
liver (9 papers, 2015 to 2025). "Very recently, APOE destabilization caused by PNPLA7 deficiency was reported to inhibit hepatic VLDL secretion and exacerbate fatty liver in db/db mice." (PMID 32776921, 2020). "Our study also showed reduced plasma and hepatic TAG and liver inflammation and fibrosis in OVX ApoE KO mice fed a Western diet." (PMID 37372993, 2023).
immune dysfunction (8 papers, 2012 to 2025). "Moreover, we observed allele dose-dependent effects, consistent with prior reports of exacerbated immune dysfunction in homozygous APOE ε4 carriers 3,25." (PMID 40709278, 2025). "This may be due to differences in lipid metabolism between two mice models that ApoE-/- mice was prone to dramatically elevate plasma total cholesterol levels 47, vascular dysfunction and immune disorders compared to wild-type mice." (PMID 37771765, 2023). "In summary, our study identifies myeloid-produced apoE as a key physiological modulator of DC antigen presentation function, paving the way for further explorations of apoE as a tool to improve the management of immune diseases." (PMID 30082772, 2018).
retinopathy (7 papers, 2005 to 2025). "Hence, the increase of ApoA1 and ApoE in the EXE group may have a positive effect against the development of retinopathy, which is the leading cause of morbidity and disability in older diabetic patients." (PMID 28713486, 2017). "Despite its association with other diabetic complications, such as retinopathy, the protective effect of ε3/ε3 genotype in DPN suggests tissue-specific mechanisms of APOE action." (PMID 41488146, 2025).
central nervous system disorder (5 papers, 2017 to 2026). A disease involving the central nervous system. "ApoE has been shown to exert anti‐inflammatory, anti‐oxidative and anti‐apoptotic properties, making it an important modulator of neuronal repair and remodeling in trauma and diseases of the central nervous system." (PMID 34423582, 2021).
peripheral neuropathy (5 papers, 2011 to 2022). A disorder affecting the peripheral nervous system. "The extent to which the observed effects of the APOE genotype and HFD on cognitive and sensorimotor parameters correlate with peripheral neuropathy was next assessed via skin IENFD and sciatic nerve electrophysiological measurements." (PMID 32075060, 2020).
hematopoietic diseases (4 papers, 2008 to 2024). "The study highlighted the role of apolipoprotein E (ApoE) in BM-targeted delivery, potentially guiding new LNP designs for extrahepatic nucleic acid delivery in hematopoietic diseases." (PMID 39852137, 2024).
gynecological diseases (3 papers, 2021 to 2024). "This brief overview details some of the recent advances, mainly from the last decade, in understanding the associations between ApoE expression and some female and male fertility problems, as well as selected female gynecological diseases and male reproductive tract disorders." (PMID 34281251, 2021).
movement disorder (3 papers, 2021 to 2026). Neurological conditions resulting in abnormal voluntary or involuntary movement, which may impact the speed, fluency, quality and ease of movement. "According to the results of the present study, in cases with ICH, ICV injection of prolactin increased PRL receptor expression in the affected regions, and increased GFAP and APOE genes expression, and caused improved movement disorders in rats." (PMID 35432801, 2021). "The results of the PRL receptor, GFAP, and APOE gene expression also confirmed the results of improving movement disorders in the behavioral section of the study." (PMID 35432801, 2021). "In the present study, ICV injection of prolactin increased APOE expression in the affected regions, and movement disorders improved." (PMID 35432801, 2021). "Therefore, astrocytes via increasing APOE expression may be involved in reduced movement disorders." (PMID 35432801, 2021).
CNS tumors (2 papers, 2019 to 2022). "Further, APOE ε4 has been linked to poorer neurocognition, memory, and executive function in adult CNS tumor patients and was linked to tau-mediated neuroinflammation and neurodegeneration, independent of amyloid-ß deposition." (PMID 35814456, 2022).
myopathy (1 paper, 2016). A disease of the muscle in which the muscle fibers do not function properly. "The purpose of this study was to determine the influence of exercise on statin-induced myopathy in a mouse model of hypercholesterolemia (ApoE-/-)." (PMID 27936249, 2016). "The purpose of this study was to determine the extent to which acute and chronic exercise can influence statin-induced myopathy in hypercholesterolemic (ApoE-/-) mice." (PMID 27936249, 2016). "The purpose of this study was to examine the influence of exercise on simvastatin-induced myopathy in hypercholesterolemic (ApoE-/-) mice." (PMID 27936249, 2016). "We hypothesized that initiation of exercise training (novel exercise) at the onset of statin administration would exacerbate statin-induced myopathy, whereas exercise training initiated prior to statin administration would protect against statin-induced myopathy, in ApoE-/- mice." (PMID 27936249, 2016). "The results from this study suggest that exercise (Nov, Acct) does not exacerbate statin-induced myopathy in ApoE-/- mice, yet statin treatment reduces activity in a manner that prevents muscle from mounting a beneficial adaptive response to training." (PMID 27936249, 2016). "However, in the present study, we did not observe any difference in myopathy or adaptation between ApoE-/- and WT mice in response to statin treatment, with or without exercise." (PMID 27936249, 2016).
neuromuscular disease (1 paper, 2015). "Moreover, several ApoE receptors, including Lrp1, Apoer2, and Lrp4 are highly expressed in muscle tissues, and ApoE genotype influences neuromuscular disease of various etiology in a similar way as in AD, suggesting that ApoE-ApoE receptor interactions could also affect muscle innervation." (PMID 25688974, 2015).
peripheral nervous system diseases (1 paper, 2023). "Moreover, ApoE alleles have been reported to influence the progression and incidence of a variety of peripheral nervous system diseases, and some studies, but not all, have suggested that ApoE status is associated with age-related changes in motor function (e.g., grip strength)." (PMID 37744392, 2023).
urological disorders (1 paper, 2018). "Another multiplex panel analysis of proteins in urine samples of BC, healthy controls and other samples with varying urological disorders revealed that urine concentrations of IL-8, MMP-9 and 10, PAI-1, ANG, and APOE were significantly increased in subjects with BC compared to healthy controls." (PMID 30544619, 2018).
APOE also shares sentences with these, for which no sentence is quoted: cognitive disorder (22 papers); Parkinsonism (16); glomerular disease (9); chronic obstructive pulmonary disease (8); concussion (7); acute myocardial infarction (6); essential hypertension (5); lymphoma (5); orthostatic hypotension (5); arterial diseases (4); corticobasal degeneration (4); end-stage renal disease (4); Leukoencephalopathy (4); primary angle-closure glaucoma (4); prostate adenocarcinoma (4); Seizure (4); thyroid (4); transient ischemic attack (4); Aphasia (3); Arrhythmia (3); cholangiocarcinoma (3); connective tissue disorder (3); Dyscalculia (3); endometrial adenocarcinoma (3); gastritis (3); gastrointestinal infections (3); hypoadiponectinemia (3); Hypoglycemia (3); kidney (3); laryngeal squamous cell carcinoma (3).
A further 283 diseases each share a sentence with APOE in 3 papers or fewer.